IDH2 (isocitrate dehydrogenase (NADP(+)) 2)
Diseases named in the same sentence as IDH2 in open-access papers (continued):
Sharing a sentence is not in itself a finding about the gene and the disease.
cartilaginous tumors (20 papers, 2012 to 2025). "IDH1/IDH2 mutations in cartilage tumors were associated with an aberrant epigenome, leading to global hypermethylation and downregulated expression of genes." (PMID 36926116, 2023). "Results showed that mutations of H3F3A were detected in all giant cell tumor of bone and malignant giant cell tumor of bone, and mutations of IDH1/2 (including 10 IDH1 and 5 IDH2) were detected in chondrogenic tumors." (PMID 35756627, 2022). "Isocitrate dehydrogenase type 1 (IDH1) and IDH2 mutations are present in close to 60% of central cartilaginous tumors: the former is present in 50–55% with IDH2 alterations being detected in ~6% of central lesions." (PMID 28834325, 2017). "Cartilage tumors frequently harbor mutations in the isocitrate dehydrogenase (IDH1 or IDH2) genes." (PMID 33266275, 2020). "Indeed, increased levels of D-2-HG have been found in cartilage tumors with an IDH1 or IDH2 mutation, and DNA hypermethylation was shown in enchondromas with an IDH1/2 mutation." (PMID 25895133, 2015). "The presence of mutations in IDH1 and IDH2 early in disease pathogenesis in malignant gliomas, myeloid malignancies, and cartilaginous tumors underscores the magnitude of the role of IDH1 and IDH2 mutations in tumorigenesis." (PMID 22885298, 2012). "IDH2, an IDH (which convert isocitrate to α-KG), is frequently mutated in cancer, particularly in secondary glioblastoma, cytogenetically normal acute myeloid leukemia (AML), cartilaginous tumors, and intrahepatic cholangiocarcinoma." (PMID 24716838, 2014). "Three types of mutations caused three types of mutant IDH1 (R132C, R132G, and R132H) genes while four types of mutations causing three types of mutant IDH2 (R172S, R172T, and R172W) genes in cartilaginous tumors; however, no mutations were detected in osteochondromas or osteosarcomas." (PMID 26161668, 2015). "H3.3 alterations are also reported in only 1/75 conventional or dedifferentiated cartilaginous tumors and are mutually exclusive of isocitrate dehydrogenase (IDH) type 1 or IDH2 substitutions which occur in 60 % of conventional or dedifferentiated cartilaginous tumors)." (PMID 25409853, 2014).
angioimmunoblastic T-cell lymphoma (18 papers, 2014 to 2025). A mature T-cell non-Hodgkin lymphoma, characterized by systemic disease and a polymorphous infiltrate involving lymph nodes and extranodal sites. "IDH2 R172K appears to be significantly linked to hematopoietic and lymphoid neoplasms and within that group seen in angioimmunoblastic T-cell lymphoma (AITL)." (PMID 33801781, 2021). "Nevertheless, since IDH2R140Q is the most frequent mutation found in AML and IDH2 mutations were also found in angioimmunoblastic T cell lymphoma, enasidenib was developed as inhibitor of mutant IDH2, inducing molecular remissions." (PMID 31847543, 2020). "Another lymphoma stems mostly from R172 mutations of IDH2, angioimmunoblastic T cell lymphoma, a subtype of nodal peripheral T cell lymphomas." (PMID 31847543, 2020). "In 10–40% of angioimmunoblastic T-cell lymphoma (AITL) were found to harbor IDH2 activating mutations, however these mutations were uncommon in other T- or B-cell lymphoid malignancies." (PMID 28785398, 2017). "However, IDH-2 mutation is more commonly associated with angioimmunoblastic T cell lymphomas, which were underrepresented in our cohort." (PMID 37796407, 2023). "IDH2 mutations were identified in approximately 20–45% of angioimmunoblastic T-cell lymphomas." (PMID 33160401, 2020). "Recurrent mutations in IDH2 are associated with angioimmunoblastic T cell lymphoma." (PMID 30050539, 2018). "In a clinical study, IDH1 and IDH2 mutations were observed in 16%–17% of patients with AML, in around 20% of angioimmunoblastic T-cell lymphomas (AITL) with worse prognosis, and in some low-frequency cancer malignancies." (PMID 31817761, 2019). "In patients with IDH2 mutated angioimmunoblastic T-cell lymphoma, the levels of intracellular and plasma 2-HG were not the same thing, and the level of intracellular 2-HG was higher than that in plasma." (PMID 33981605, 2021). "Conversely, no mutations were found in RHOA, IDH2, and CD28, known to occur in angioimmunoblastic T-cell lymphoma and other nodal T-cell lymphomas of T follicular helper origin." (PMID 31028364, 2020).
diffuse astrocytoma (14 papers, 2014 to 2025). A low-grade (WHO grade II) astrocytic neoplasm. "The presence of isocitrate dehydrogenase 1 (IDH1) and 2 (IDH2) mutations has been observed in diffuse astrocytomas (WHO grade II) and anaplastic astrocytomas (WHO grade III)." (PMID 41466163, 2025). "Among patients previously diagnosed as IDH-mutant GBM, anaplastic astrocytoma, or diffuse astrocytoma, 60 cases exhibited IDH1 or IDH2 mutations and were reclassified as A-IDHm." (PMID 38893152, 2024). "Symptomatic tumor progression was suspected in 2018, leading to a surgical tumor biopsy that demonstrated WHO grade 4 IDH1 and IDH2 mutant diffuse astrocytoma." (PMID 37077830, 2023). "In 2009, Yan's study indicated that mutations of IDH1 and IDH2 occurred in majority of several types of malignant gliomas and reported the incidence of IDH1/2 mutation in diffuse astrocytoma (90%), anaplastic astrocytoma (73%) primary GBM (5%) and secondary GBM (85%)." (PMID 24810474, 2014).
intrahepatic cholangiocarcinoma (13 papers, 2014 to 2026). A carcinoma that arises from the intrahepatic bile duct epithelium in any site of the intrahepatic biliary tree. "IDH1 and IDH2 isoforms are frequently mutated in various cancers, including glioma, acute myeloid leukemia, thyroid carcinomas, cartilaginous tumors, and intrahepatic cholangiocarcinoma (ICC)." (PMID 40567251, 2025). "For instance, mutations in the IDH1 and IDH2 genes, as well as alterations in the FGFR2 gene, are more commonly associated with intrahepatic cholangiocarcinoma." (PMID 40075667, 2025).
myelofibrosis (12 papers, 2016 to 2024). A partial or complete replacement of the bone marrow stroma by fibrous tissue. "IDH2 mutation is an unfavorable prognostic factor in patients with primary myelofibrosis (PMF) but its effect on myelofibrosis (MF) remains largely unclear." (PMID 39157630, 2024). "In another study, 166 patients with chronic-phase MPN (77 PMF, two post-PV myelofibrosis, two post-ET myelofibrosis, 47 ET, and 38 PV) and 34 blast-phase MPN were screened for IDH1 and IDH2 mutations." (PMID 26668680, 2016). "Retrospective analysis of the initial bone marrow sample in the myelofibrosis stage was negative for the IDH2 p.R140Q mutation when analyzed by both superRCA and ddPCR assays, indicating a clonal evolution upon AML transformation." (PMID 35821208, 2022). "The largest study that investigated the frequency of IDH1 and IDH2 mutations in Ph-negative MPN patients included 594 ET, 421 PV, 312 PMF, 95 post-PV/ET myelofibrosis and 51 blast-phase MPN patients." (PMID 26668680, 2016).
Ollier disease (12 papers, 2014 to 2026). A rare primary bone dysplasia disorder characterized by the development of multiple mainly unilateral or asymmetrically distributed enchondromas throughout the metaphyses of the long bones. "It is clear that somatic mosaic isocitrate dehydrogenase type 1 (IDH1) and isocitrate dehydrogenase type 2 (IDH2) mutations are associated with Maffucci’s syndrome and Ollier disease." (PMID 34790172, 2021). "Interestingly, case #13 was identified as enchondromatosis (Ollier-Maffucci syndrome with a germline IDH2 R172G mutation, also found in the tumor)." (PMID 38581034, 2024). "It has been clear that somatic mosaic isocitrate dehydrogenase type 1 (IDH1) or isocitrate dehydrogenase type 2 (IDH2) mutations are associated with Maffucci’s syndrome and Ollier disease, but the mechanisms underlying hemangiomas of the Maffucci’s syndrome is still obscure." (PMID 34790172, 2021). "It will be of interest to determine whether mutations in IDH1 or IDH2, which cause Ollier disease and Maffucci syndrome, affect chondrocyte organization and terminal differentiation in a similar manner to SHP2 depletion." (PMID 24875294, 2014). "Ollier disease is due to early post-zygotic IDH mutations, leading to somatic mosaic mutations of IDH1 or IDH2." (PMID 35884525, 2022). "Patients with Ollier disease and Maffucci syndrome, due to somatic gain-of-function mutations in IDH1 or IDH2, develop enchondromas." (PMID 24875294, 2014). "The etiology of Ollier disease is unknown, but it is linked with somatic heterozygous mutations in IDH1 or IDH2 genes." (PMID 34393643, 2021). "The estimated prevalence of Ollier disease is 1 in 100,000 and while it is linked with somatic heterozygous mutations in IDH1 or IDH2 genes, exact etiology is unknown." (PMID 34393643, 2021). "JGCTs may occur in enchondromatosis-associated Ollier disease and Maffucci syndrome, both representing likely nonhereditary conditions, in which somatic IDH1 and IDH2 mutations have been reported." (PMID 37796616, 2023).
cardiac hypertrophy (10 papers, 2019 to 2024). "However, IDH2 deficiency in mice is sufficient to cause mitochondrial dysfunction and cardiac hypertrophy." (PMID 35985423, 2022). "with the loss of IDH2 activity long appreciated to precede cardiac hypertrophy." (PMID 31434333, 2019). "Among these gene pairs, IDH2 has been shown to play a role in preventing oxidative stress in cardiac hypertrophy in mice and FHL2 has been shown to repress pathological cardiac remodeling." (PMID 38780967, 2024). "A decrease in IDH2 activity leads to hypertrophy in cardiomyocyte cell lines in rodent LVH models, with the loss of IDH2 activity long appreciated to precede cardiac hypertrophy." (PMID 31434333, 2019). "Sirtuin-3 also regulates mitochondria functioning and cardiac hypertrophy via the deacetylation of isocitrate dehydrogenase (IDH2)." (PMID 31434333, 2019). "In several organs, the role of IDH2 has been determined to be essential for maintenance of mitochondrial glutathione status to prevent diseases including cardiac hypertrophy, and renal dysfunction." (PMID 30508699, 2019). "This hypothesis is further supported by observations that IDH2 knockout mice exhibit cardiac hypertrophy and have a greater percentage of large skeletal muscle fibers than wild‐type mice." (PMID 38453353, 2024). "Fatty acid oxidation (Acadm, Etfdh, Acadl, Acadvl, Eci1, Hadh, Phyh, Acaa2, Hadha, Hadhb, Cd36), glucose metabolism (Dld, Pdha1, Pgam1, Pgam2, Acss1, Ldhb, Fh1, Slc2a4, Aldh6a1), TCA cycle (Aco2, Dld, Fh1, Ogdh, Sucla2, Sdha, Idh3b, Idh2) were up-regulated by hispidulin in cardiac hypertrophy." (PMID 33324687, 2020). "Downregulation of IDH2 and α-KGDH activity reflects mitochondrial oxidative stress in early cardiac hypertrophy." (PMID 39594567, 2024).
sarcoma (10 papers, 2015 to 2025). A usually aggressive malignant neoplasm of the soft tissue or bone. "IDH2 mutations have been observed in several cancer types, including sarcomas, hematologic malignancies, colon cancer and brain cancer." (PMID 33952272, 2021). "In the same study, IDH2 mutant tumor histology and immunohistochemistry resembled that of poorly differentiated sarcomas, suggesting that IDH mutation may influence disease progression and dedifferentiation." (PMID 40364090, 2025). "On the other hand, the macrodissected WDCS and high-grade sarcoma components in DDCS cases showed similar methylation profiles, regardless of IDH1/IDH2 mutational status, suggesting that the observed IDH1/IDH2-associated methylation pattern is an early event in DDCS." (PMID 36926116, 2023).
colon carcinoma (9 papers, 2012 to 2025). "IDH2-knockout mice were exposed to a dietary carcinogen, 2-amino-1-methyl-6-phenylimidazo(4,5-b)pyridine (PhIP), to validate IDH2’s role in colon cancer development." (PMID 41258072, 2025). "The expression of IDH2 was significantly downregulated in the early stages but upregulated in advanced stages of colon carcinoma compared to peritumor tissues." (PMID 36497259, 2022). "In this study, we observed that IDH2 expression was significantly downregulated in early phase but was upregulated in advanced phase colon carcinoma compared to peritumoral tissues." (PMID 23226729, 2012). "In this study, we observed that IDH2 is downregulated in in situ colonic carcinoma and upregulated in infiltrating colonic carcinoma compared with normal tissues by cDNA microarray." (PMID 23226729, 2012). "Our data demonstrate that IDH2 was significantly downregulated in early stage (in situ carcinoma) and upregulated in advanced stage (infiltrating carcinoma) colon cancer compared to peritumor tissue." (PMID 23226729, 2012). "The growth of colon cancer cell lines was inhibited by IDH2-siRNA and increased after transfection with IDH2 overexpressing plasmids, indicating that IDH2 might play a role in the development of colon carcinoma." (PMID 36497259, 2022). "To identify whether the expression level of IDH2 affects the proliferation of colonic carcinoma cells, we assayed the growth of the HCT-8 colonic carcinoma cell line after transfection with IDH2-siRNA or the overexpression plasmid." (PMID 23226729, 2012). "In addition, we assayed the alteration of IDH activity by IDH2 in transfected cells to explore the influence of the enzyme on the proliferation of the HCT-8 colon carcinoma cell line." (PMID 23226729, 2012). "In addition, we demonstrated that the growth of a colon carcinoma cell line was inhibited by IDH2-siRNA and increased following transfection with an IDH2-overexpressing plasmid." (PMID 23226729, 2012). "To test this hypothesis, we used overexpression and siRNA-mediated knockdown of IDH2 to investigate the role of the gene in the growth of colonic carcinoma HCT-8 cells using an MTT assay." (PMID 23226729, 2012). "To test this hypothesis, we reduced IDH2 expression by transfecting IDH2-siRNA or overexpressed the gene by transiently transfecting the IDH2 plasmid to investigate the role of IDH2 in the growth of HCT-8 colon carcinoma cells." (PMID 23226729, 2012). "Based on these findings, we hypothesize that the abnormal expression level of IDH2 contributes to the development of colon carcinoma, which is in agreement with previous studies." (PMID 23226729, 2012). "Although IDH1 mutations have been reported in colon cancer, no IDH2 mutations in this cancer subtype have been identified to date." (PMID 23226729, 2012). "Although mutations and abnormal expression of IDH2 have been identified in several types of cancers, mutations in the IDH2 gene have not been described in colon cancer." (PMID 23226729, 2012). "This indicates that IDH2 may have a role in the development of colon cancer." (PMID 23226729, 2012). "Our results indicated that IDH2 may play an important role in the development of colon cancer." (PMID 23226729, 2012). "Interestingly, our recent study showed that IDH2 was overexpressed in colorectal cancer cells and a knockdown of IDH2 in HCT-116 and HT-29 cells led to a decrease in α-KG, suggesting that IDH2 might mainly catalyze the oxidative TCA metabolism in colon cancer cells." (PMID 35313945, 2022). "Therefore, IDH2 may be an important factor in the development of colon cancer." (PMID 23226729, 2012). "Although IDH2 has been demonstrated to be upregulated in several types of human cancers, no studies have shown alteration of IDH2 in colon cancer." (PMID 23226729, 2012). "The release of IDH2 is not specific to NSCLC, but it could also occur in other cancer cell lines, such as colon cancer cell lines HCT116 and HT29." (PMID 29465809, 2018).
prostate carcinoma (9 papers, 2017 to 2024). A carcinoma that arises from epithelial cells of the prostate gland. "Loss of IDH2 has been shown to impair oxidative bioenergetics, elevate reactive oxygen species (ROS) production, and promote exaggerated mitochondrial dynamics in prostate cancer cells." (PMID 35004842, 2021). "IDH1/IDH2 genes are mutated in 1–3% of all prostate cancer cases." (PMID 31366128, 2019). "The three-fold decrease in IDH2 expression normalised the TCA cycle in prostate cancer cells, and the 4.3-fold increase in FH expression inhibited fumarate build-up in prostate cancer cells and deactivated the angiogenic factor hypoxia-inducible factor 1-alpha." (PMID 36771106, 2023).
cardiomyopathy (8 papers, 2016 to 2025). A disease of the heart muscle or myocardium proper. "Conditional expression of transgenic IDH2 mutation in knock-in mice caused cardiomyopathy and neurodegeneration instead." (PMID 30416682, 2018). "Moreover, germline IDH2 mutations phenocopied cardiomyopathy and muscular dystrophy, as seen in D-2-hydroxyglutaric aciduria patients harboring autosomal dominant IDH2 mutations." (PMID 35203456, 2022). "However, cardiomyopathy in D2HGA type II may also be related to NADPH deficiency resulting from consumption of this co-factor in the reduction of αKG to 2HG by mutant IDH2." (PMID 27469509, 2016). "Thus, downregulation of IDH2 appears to occur specifically in cardiomyopathies involving eccentric hypertrophy." (PMID 38509128, 2024). "IDH2 caused the up-regulation of NAD, which may lead to the cardiomyopathy of KD." (PMID 29321553, 2018). "Malonylation of proteins especially IDH2, a key enzyme in the TCA cycle and mitochondria, has been explored in cardiomyopathy." (PMID 36577755, 2022). "Type II (IDH2 mutation) is associated with earlier onset, more severe developmental delay, higher seizure frequency and reduced life expectancy than type I (D2HGDH mutation), and ∼50 % of patients have cardiomyopathy, which is not observed in type I." (PMID 27469509, 2016).
colorectal cancer (8 papers, 2015 to 2025). A primary or metastatic malignant neoplasm that affects the colon or rectum. "The IDH1 and IDH2 mutations are also present in 0.9% of colorectal cancer, associated with the BRAF V600E mutation, in 0.5% of non-small cell lung carcinoma (NSCLC), co-existing with KRAS mutations and in melanoma, occurring with NRAS mutations." (PMID 39123479, 2024). "Therefore, alterations in IDH1 and IDH2 expression might play different roles during the development of colorectal cancer." (PMID 26376762, 2015). "Since IDH2 also contributes to NADPH production and purine biosynthesis to facilitate cancer cell growth, we detected NADPH and ROS levels in colorectal cancer cells." (PMID 30367038, 2018). "This demonstrated D-2HG levels to be elevated in human colorectal cancer tissues compared to non-cancerous tissues, in the absence of mutations of IDH1 or IDH2." (PMID 27824159, 2016). "On the other hand, mutant IDH1 and IDH2 did not exhibit significant increase of intracellular lactate level in HCT116 cells, indicating that augmented Glut1 expression induced by IDH1/2 mutants may not be sufficient to affect glycolytic pathway in colorectal cancer cells." (PMID 34516556, 2021).